CD4 (CD4 molecule)
Diseases named in the same sentence as CD4 in open-access papers (continued):
Sharing a sentence is not in itself a finding about the gene and the disease.
influenza (continued). "However, live attenuated influenza vaccine (LAIV) mimics natural infection with viral replication in the upper respiratory tract and induces multifaceted immune responses, including antibodies and CD4+ and CD8+ T cells." (PMID 28368530, 2017). "The mounting evidence that CD4 CTL are an important component of protective immunity against many infectious diseases suggests that eliciting such cytotoxic responses may boost vaccine efficacy against infections such as HIV and influenza." (PMID 28167943, 2017). "It is possible that CD4 responses to previous influenza infections may not correlate closely enough with measured antibody responses to hemagglutinin." (PMID 28193244, 2017). "In this study to gain better understanding of cross-protective influenza vaccines, we compared immunogenicity and efficacy of M2e5x VLP, H5 hemagglutinin VLP (HA VLP), and inactivated H3N2 virus (H3N2i) in wild-type strains of BALB/c and C57BL/6 mice, and CD4 and CD8 knockout (KO) mice." (PMID 29276514, 2017). "Importantly, studies of influenza infection in mice have demonstrated that the generation of CD4 CTL does not necessarily require prolonged, chronic antigen stimulation, but can instead occur during acute infection." (PMID 28167943, 2017). "During influenza infection, the trafficking and induction of CD4 CTL in the lung coincides with the expression of MHC class II molecules on lung epithelial cells at 5 days postinfection, which is likely critical for the contribution of CD4 CTL to protection from lethal infection." (PMID 28167943, 2017). "As had been observed in response to influenza infection, antigen-reactive CD4 T cells partitioned between Tfh and NonTfh at ratios ranging from near equivalent (HA 144 and HA 162, NP 97) to those with a higher representation in the Tfh population (e.g. NP 264 and HA 334)." (PMID 27329272, 2016). "Moreover, CD4+ T cells are involved in hypersecretion in smokers, which are known but not essential for clearance of influenza in mice." (PMID 26877172, 2016). "In addition to production of NP-specific antibodies, young, but not aged, NP vaccinated mice given a subsequent influenza infection also exhibit NP-specific CD4 T cells in the lungs and spleen very early (day 5) during infection." (PMID 27177221, 2016). "It was shown that Th1 clones, but not Th2 clones, could lyse influenza infected targets and indicated that CD4 CTL could be generated after vaccination as well as live infection." (PMID 27014272, 2016). "Moreover, the observation that both CD4+ and CD8+ T-cell responses are directed against epitopes from conserved internal antigens in the convalescent phase of infection may guide universal influenza vaccine development." (PMID 26606759, 2015). "However in a human, high dose challenge model of seasonal influenza A virus, pre-existing influenza-specific CD4+ T-cells, rather than CD8+ T-cells, correlated with protection against mild disease." (PMID 26606759, 2015). "In vitro studies demonstrated the protective role of CD4+ T-cell reactivity against previously the unencountered avian influenza (H5N1) strain; this protection was shown to be due to the presence of commonly conserved and shared epitopes with seasonal influenza strains, H1N1 and H3N2." (PMID 24609014, 2014). "Interestingly, in a challenge study with volunteers deliberately infected with H3N2, the numbers of pre-existing influenza-specific CD4+, but not CD8+, T cells were found to correlate with lower virus shedding and less severe, shorter illness." (PMID 24971078, 2014).
influenza (continued). "However, the human CD4 T cell response to influenza is mainly a Th1 response, with no IL-4+ or IL-17+ cells detectable in the influenza specific 2+γ- population." (PMID 24788814, 2014). "To test whether the presence of memory CD4 T cells prior to vaccination impacts the magnitude of the post vaccine CD4 T cell response, we examined subjects with or without robust pre-existing influenza-specific CD4 T cells." (PMID 24155927, 2013). "We hypothesized that responses against TIV might differ based on the presence or absence of influenza virus-specific memory CD4 T cells from previous infection or vaccinations and that such pre-existing immunity might differ between aged and young individuals." (PMID 24155927, 2013). "In addition to antibodies, cross-reactive CD4+ and CD8+ T cells may also play an important role in protection against influenza." (PMID 23555631, 2013). "Our findings lead to the conclusion that recall responses from CD4+ memory T cells generated by previous exposure to seasonal H1N1 viruses and also identifies a highly conserved, novel immunodominant CD4+ T cell epitope that would be a promising target for universal epitope-based influenza vaccines." (PMID 23641949, 2013). "These interactions may be due to residual antigen presentation which plays a significant role in the development of memory CD4+ T cells after influenza infection, but may not always be necessary for CD8+ T cell memory development." (PMID 23533579, 2013). "However, influenza does not activate DR5 expression on CD4+ T cells, and TRAIL-DR5-mediated apoptosis of CD4+ T cells is not observed." (PMID 22412938, 2012). "Following 12 h ex vivo stimulation with the LACK158–173 peptide, a distinct LACK158–173+CD4+ T cell population in the spleens of vaccinated mice produced IFN-γ, but no IL-4 (data not shown), indicating that LACK158–173 vaccination in the context of influenza induces a Th1-bias." (PMID 22470440, 2012). "In contrast, a significant influenza-driven recall response was only generated in the CD4+CD8+ subset (6±1% CFSElow cells, P<0.01, n = 3), but not in the CD4+CD8− and CD4−CD8+ subsets (1±0% and 2±0.3% CFSElow cells, P>0.94, n = 3), in pigs vaccinated with the non-adjuvanted whole vaccine." (PMID 22427834, 2012). "No influenza-derived CD8+ or CD4+ T cell epitopes have been reported for infected macaques, so we could not use epitope-specific reagents such as minimal optimal peptides or MHC tetrameric complexes to measure cellular immune responses in these animals." (PMID 22102819, 2011). "Multivariable logistical regression was controlledfor baseline variables related to HIV therapy, HIV viral load, CD4 count,age, sex, weight, tobacco use, viral hepatitis co-infection, history ofprior influenza vaccination, and lack of baseline influenza seroprotection(HAI titres ≤10)." (PMID 21512577, 2011). "This suggests that CD4 T cells may not be required for viral clearance consistent with findings that CD8 T cells are more important for survival from highly virulent influenza infection in mice." (PMID 20540811, 2010). "However, other data clearly demonstrate that B cells can also produce anti-influenza IgA, IgM, and IgG responses independent of CD4 helper T cells." (PMID 18258091, 2008). "Thus, our results demonstrate that clinical disease following influenza infection is enhanced in the absence of CD59a, and that severity correlated with the infiltration of neutrophils and CD4+ T cells into the lungs of the infected mice." (PMID 17429844, 2007). "However, spike-specific CD4+ T cells were mainly of the Tcm phenotype, stable at 3 mo postinfection up to 24 mo or postvaccination, which was the case for both long COVID and non-LC, and influenza-specific CD8+ T cells." (PMID 39284068, 2024).
influenza (continued). "Similarly, suppressive adaptive immune responses were observed in patients with severe influenza, which manifested as decreased levels of key lymphocyte populations, including activated CD8 + T cells, B cells, CD4 + T cells, and memory CD8 + T cells, B cells, and CD4 + T cells." (PMID 38454348, 2024). "During the first week post-vaccination, TREG cells (CD3+CD4+FOXP3+) harbored the highest predictive value (AUC approximately 0.9) with respect to the other cell compartments, thus substantiating the hypothesized role of TREG cells as a driving force that determine influenza vaccine responsiveness." (PMID 36371426, 2022). "Collective differences between these reports suggest that CD4+ and CD8+ T cells may be differentially affected by immunosenescence, and further study is warranted in order to fully understand the effects of adaptive immunosenescence on cellular immunity to influenza." (PMID 31528180, 2019). "We observed a vaccine-induced fold-increase (2.0) in influenza-specific CD4 T cells among pregnant subjects that was lower than in non-pregnant subjects (2.5 fold), and at the low end of the range of vaccine-induced CD4 changes reported by others for non-pregnant healthy adults." (PMID 28723925, 2017). "However, the decreased frequency of CD4 T cells in post-menopausal women receiving ET did not impact the T cell response to influenza vaccination since we reported a comparable increase in the frequency of influenza T cells in all three groups." (PMID 26859566, 2016). "Thus, while the total number of CD4 T cells trafficking to the lungs in unvaccinated influenza infected aged mice is not significantly different, the Th subset distribution of these cells is dramatically altered and could have an impact on protective immunity." (PMID 27177221, 2016). "However, the lack of difference in IL-4 and IFNγ production could be attributed to the lack of strong CD4+ or CD8+ T cells epitopes in influenza HA protein in C57BL/6 mice that is restricted by H-2b47." (PMID 27404789, 2016). "Aside from CD8+ T-cell responses, it has been established that T-cell help (in the form of CD4+ T-cells) and B-cell responses should not be overlooked, and therefore a vaccine concept that utilizes both T-cell and B-cell responses should be pursued to obtain a universal influenza vaccine." (PMID 25344321, 2015). "However, not all influenza-specific CD4 T cells express both IL-2 and IFNγ." (PMID 24788814, 2014). "In addition, the comparable expansion of split-flu specific CD4 T cells and diminished neutrophil responses suggests that either cross-neutralizing antibodies or cross-reactive CD8 T-cells were responsible for the protection from influenza challenge in primed mice." (PMID 24465206, 2014). "However, whether cross-reactive antibodies to NA and CD4 T cells would be protective against illness and death, especially from influenza (H5N1) infection is not known." (PMID 18258091, 2008). "Unlike another internal influenza antigen, PB1, which is equally targeted by CD4+ and CD8+ T cells, NP is believed to be a major target for CD8+ CTLs." (PMID 38140152, 2023). "Influenza challenge results in a strongly polarised type-1 response with production of interferon (IFN)-γ and dominance of CXCR3-expressing CD4+ and CD8+ T cells, with no other polarised T-cell response observed." (PMID 37696824, 2023). "A correlation between lesser viral shedding and milder disease and preexisting CD4+, but not CD8+, T lymphocytes reacting to influenza internal proteins was reported." (PMID 36992177, 2023). "A comparative human study of influenza, RSV and non-typeable haemophilus influenza (NTHi) demonstrated that antigen-specific CD4+ TRM cells were in low proportion in peripheral blood as compared to the lungs." (PMID 36211412, 2022). "A functional lack of CD200 results in pathology with influenza-specific NP366–374 CD8+ T cell infiltration and other pathologies in which CD4+ T cells also play a role." (PMID 33562512, 2021).
influenza (continued). "The lack of heterosubtypic immunity with current influenza vaccines is due to the fact that the CD8+ and CD4+ T cells tend to be specific for HA and NA from homosubtypic strains." (PMID 34835255, 2021). "In mice, LAIV vaccination increases the frequency of CD4+ and CD8+ T cells in the lung and cytokine production upon influenza restimulation compared with the inactivated virus or no vaccine administration." (PMID 33497364, 2021). "Anti-influenza vaccine via the ID route in humans induced both effector CD4 and CD8 T cell responses, whereas IM injection induced strong effector CD4 in the absence of CD8 T cells." (PMID 34578148, 2021). "It is also important to mention that I am not discussing here the important roles of CD4+ and CD8+ T cell responses in modulating the immune response elicited by influenza vaccines, as this is outside the scope of this perspective." (PMID 30248996, 2018). "Aside from the CD8+ and CD4+ subsets of TRM, a subset of NK1.1+ double negative T memory cells which reside in the lungs also play a role in influenza infection." (PMID 30038624, 2018). "In contrast to Treg cells from naïve SPF mice, human CD4+CD127lowCD25+ Treg cells in peripheral blood already express a substantial amount of CXCR3 at steady state and influenza vaccination did not induce significant changes in their frequency." (PMID 29951069, 2018). "We show that CD30 is expressed on activated but not resting CD4 and CD8 T cells in vitro, as well as on regulatory T cells and marginally on T helper 1 cells in vivo during influenza infection." (PMID 28993768, 2017). "We confirmed that that modest influenza-specific CD4 T cell increases, but not CD8 T cell responses, can be detected in pregnant women following influenza vaccination." (PMID 28723925, 2017). "Although influenza‐specific CD4 and CD8 T cells are generated against conserved influenza antigens/peptides, they do not appear to be generated at a level that is enough to afford protection year after year." (PMID 28146323, 2017). "While one of the classical functions of CD4 T cells is to help CD8 T cell effector generation, such help is not important for an effective primary immune response to influenza." (PMID 27148257, 2016). "Finally, we demonstrated the importance of CD4+Tfh cells rather than iNKTfh cells for inducing efficient antibody production after aAVC vaccination and could show protection using this vaccination strategy in an influenza infection model." (PMID 27739478, 2016). "While low CD4 cell counts and HIV viremia are important determinants of vaccine response, they do not fully explain the reduced immunogenicity to influenza vaccine observed in this population, indicating that other factors contribute as well." (PMID 26576297, 2015). "Interestingly, for the influenza vaccine-induced Ab response, it was CD4 T cell activation rather than CD8 T cell activation that showed this inverse relationship, suggesting that immune activation may have different outcomes that are specific for each cell type." (PMID 24236161, 2013). "PBMCs from pneumococcal colonised (n = 10) and non-colonised (n = 8) adults stimulated ex vivo with influenza antigen elicited similar frequencies of TNF+, IL-17A+ and IFNγ+ CD4+ memory T-cells." (PMID 23555269, 2013). "We observed low response rates to the 2009 pandemic influenza vaccine among HIV-infected individuals without pre-existing antibodies against H1N1 HA and a minor transient fall in CD4+ T cell numbers, which was accentuated in responders." (PMID 22937824, 2012). "Age, gender, time since immunization, pre- and post-immunization CD4+ T cell counts, pre- and post- HIV viral load, and CD4+ T cell nadir did not independently affect response to influenza vaccine." (PMID 22937824, 2012).
influenza (continued). "Although initiation of HAART managed to suppress viral load and boost the CD4 count, it did not restore the influenza-specific immunity even after 12months on HAART, suggesting that this intervention alone may not rapidly reduce the risk of influenza-related complications." (PMID 22715399, 2012). "We found that influenza-specific IFNγ production by CD4 and perhaps CD8 T cells or the absence of the KLRG1+CD57+ influenza-specific tetramer positive population each independently predict influenza antibody responses upon vaccination." (PMID 21887299, 2011). "As expected, the CD8 T cell-specific 9-mer peptide HA189-197 did not stimulate any CD4 T-cell responses, nor did the MVA wild-type virus induce detectable frequencies of influenza-specific CD4 T-cells in the mice." (PMID 21283631, 2011). "Multifunctional CD8 T cells associate with non-progressors in HIV infection, multifunctional CD4 and CD8 T cells characterise protective immunity in the lungs of influenza infected mice (reviewed by Kohlmeier and Woodland,)." (PMID 21720558, 2011). "We observed no major changes in the proportions of functional influenza-specific CD8 and CD4 T cell responses of young or older donors post-vaccination, indicating that there is little T cell response to this vaccine." (PMID 21887299, 2011). "The CD4/CD8 ratio of patients with the other infection types, including hospitalized cases of influenza, did not significantly differ from the controls." (PMID 20626864, 2010). "The PCN-induced iBALT structures contained B cells, CD4 T cells, follicular dendritic cells, and CD8 T cells (data not shown), similar to that of iBALT structures induced by influenza infection and seen in other non-inducible secondary lymphoid tissues." (PMID 19774076, 2009). "In mice not subjected to smoke exposure, intensity of CD25α staining on both CD4+ and CD8+ cells in BALF was low for influenza and no treatment mice." (PMID 18627612, 2008). "The influenza vaccine recruits CD4 + T cells to the choroid plexus to promote hippocampal neurogenesis in pregnant mice, while CD8 + T cells infiltrating the brain, rather than CD4 + T cells, suppress neurogenesis following hepatitis B vaccination." (PMID 41146571, 2025). "Collectively, these results establish that the lung-residing T cells, potentially both CD4+ and CD8+ T cells, are involved in but not solely responsible for the influenza-targeting protection afforded by rTTV-RBD-HA2 through the systemic priming-mucosal boosting regimen." (PMID 39669563, 2024). "In contrast to previous studies, the introduction of M-001 as a primer before administering quadrivalent inactivated influenza vaccine (IIV4) did not increase antibody titres to IIV4, although it did result in the expansion of the multifunctional CD4+ T cells subset over a 6-month period." (PMID 39596049, 2024). "Our study included naive CD8 and CD4 T cells in the LN, antigen-specific effector CD8 T cells responding to infection in the villi and lung (influenza-infected lung), and non-antigen specifically activated effector CD8 T cells in the LPS-inflamed lung in a model of acute lung injury." (PMID 37870221, 2023). "However, in infectious models that generate strong inflammatory responses such as influenza infection, the primary CD8 T cell responses are largely independent of CD4 T cell help, potentially due to the direct activation of DCs by robust TLR signaling." (PMID 34572004, 2021). "Furthermore, we found higher frequencies of all the CD4 and CD8 maturational subsets expressing the proliferation marker Ki67 in the non-responders to the influenza vaccine than the responders." (PMID 31312227, 2019). "Indeed, those individuals with lower CD4+ and CD8+ T cell numbers following ex vivo stimulation with live flu virus had a higher rate of laboratory diagnosed flu as opposed to those subjects that had higher CD4+ and CD8+ T cell numbers." (PMID 29616390, 2018).